CCL15 (C-C motif chemokine ligand 15)
Description:
Chemotactic factor that attracts T-cells and monocytes, but not neutrophils, eosinophils, or B-cells. Acts mainly via CC chemokine receptor CCR1. Also binds to CCR3. CCL15(22-92), CCL15(25-92) and CCL15(29-92) are more potent chemoattractants than the CCL15.
Synonyms: HCC-2; LKN-1; MIP-5; NCC3; SCYA15; NCC-3; SCYL3; MIP-1d; HMRP-2B; LKN1; MIP-1 delta; MRP-2B; SY15
Tractability: Small molecule: a structure with a bound ligand is known. Antibody: UniProt places it where antibodies can reach, with medium confidence; UniProt predicts a signal peptide or a membrane-spanning region; its Gene Ontology location is reachable by antibodies, with medium confidence.
Gene: Protein-coding gene on chromosome 17 (35,996,440 to 36,001,553, reverse strand). Ensembl gene ENSG00000275718.
Subcellular location: Secreted
Subcellular location (Human Protein Atlas): Golgi apparatus; Vesicles; Predicted to be secreted
Gene Ontology:
Molecular function: chemoattractant activity; chemokine activity; CCR chemokine receptor binding; signaling receptor binding
Biological process: positive regulation of inflammatory response; antimicrobial humoral immune response mediated by antimicrobial peptide; cell chemotaxis; cell-cell signaling; chemokine-mediated signaling pathway; chemotaxis; inflammatory response; intracellular calcium ion homeostasis; positive regulation of cell migration; signal transduction; immune response; positive chemotaxis
Cellular component: extracellular region
Genetic constraint (gnomAD): Loss-of-function variants: 8 observed, 9.4 expected, observed/expected ratio (o/e) 0.85, 90% interval 0.5 to 1.52. That is too few expected variants to judge how well the gene tolerates losing a copy. Missense variants: 124 observed, 136.46 expected, observed/expected ratio (o/e) 0.91, 90% interval 0.79 to 1.05. Synonymous variants: 50 observed, 50.31 expected, observed/expected ratio (o/e) 0.99, 90% interval 0.79 to 1.26.
Homologues: Orthologues: chimpanzee CCL15 (98% identical), macaque CCL15 (84% identical), dog CCL23 (42% identical), mouse Ccl9 (42% identical), mouse Ccl6 (41% identical), rat Ccl9 (41% identical), zebrafish ccl35.1 (25% identical), zebrafish ccl35.2 (25% identical). Paralogues in human: CCL23 (72% identical), CCL3 (38% identical), CCL3L3 (38% identical), CCL4 (34% identical), CCL18 (33% identical), CCL8 (33% identical), CCL14 (32% identical), CCL11 (31% identical), CCL4L2 (31% identical), CCL5 (31% identical), CCL7 (31% identical), CCL21 (29% identical), and 14 more.
Diseases named in the same sentence as CCL15 in open-access papers:
CCL15 is named in the same sentence as 86 diseases in open-access papers, as found by Europe PMC text mining. Sharing a sentence is not in itself a finding about the gene and the disease. The quoted sentences say what the papers report.
colorectal cancer (17 papers, 2019 to 2025). A primary or metastatic malignant neoplasm that affects the colon or rectum. "Colorectal cancer models have shown that CCL15 causes tumor-associated neutrophils (TAN) recruitment to the tumor niche via CCR1 on these cells." (PMID 33182504, 2020). "Furthermore, the same group showed that colorectal cancer cells with the loss of the tumor suppressor SMAD4 secreted CCL15 and recruited CCR1+ myeloid cells to assist tumor invasion in colorectal cancer patients." (PMID 35267547, 2022). "In colorectal cancer, CCL15 facilitates lung metastasis by recruiting neutrophils, and promotes liver metastasis by attracting myeloid cells." (PMID 40740234, 2025). "With the progression of tumor, chemokines such as CCL2, CCL7, CCL8, and CCL15 in the microenvironment of colorectal cancer gradually increase, recruiting monocytes and Th1 cells to the tumor region." (PMID 37063892, 2023). "That is why the aim of our study was an attempt to clarify and to assess the usefulness of selected CC-chemokine measurement (CCL2, CCL4 and CCL15) in patients with colorectal cancer compared to the healthy volunteer group." (PMID 35407400, 2022). "Accumulating evidence suggested that CCL15 plays an essential role in several types of cancer, including lung cancer, colorectal cancer, and hepatocellular carcinoma." (PMID 33790943, 2021). "The knockdown of CCL15 in colorectal cancer cells was shown to diminish CCR1+ accumulation, and tumor growth was suppressed." (PMID 32443699, 2020). "In the sera of colorectal cancer patients there is a noted increase in CCL15 and a striking intratumoral presence of MDSCs expressing its receptor CCR1." (PMID 34458892, 2020). "Most of the CCR1+ cells were G-MDSCs, and the CCL15 levels in the sera of colorectal cancer patients were significantly higher than those in controls." (PMID 32443699, 2020). "Accumulating loss of SMAD4 leads to up-regulation of CCL15 and CCR1 expression, followed by higher activity and expression of MMP-9, ultimately causing colorectal cancer malignance." (PMID 30979374, 2019). "SMAD4 deletion promotes colorectal cancer (CRC) expression of C-C Motif Chemokine Ligand 15 (CCL15) and recruits the CCR1 TAN (CCL15-CCR1 axis) with arginase-1 (ARG-1) and matrix metalloproteinase 9 (MMP-9) activities, thereby forming a pre-metastatic niche for disseminated tumor cells (e." (PMID 40160822, 2025). "In addition, in hepatocellular carcinoma and colorectal cancer, CCL15 is responsible for recruiting TAM and myeloid-derived suppressor cells (MDSC) and for recruiting mesenchymal stem cells (MSC) into the tumor niche." (PMID 33182504, 2020). "Mechanistically, TRIM47 promotes the ubiquitination and degration of SMAD4 by interacting with SMAD4, and further increases the levels of C-C motif chemokine ligand 15 (CCL15) and C-C motif chemokine receptor 1 (CCR1), ultimately causing poor outcome of colorectal cancer." (PMID 30979374, 2019). "Although a few reports showed that overexpressed CCL15 in cancer cells may be used as an indicator of poor patient outcomes of hepatocellular carcinoma and colorectal cancer metastasis, the mechanisms used by CCL15 within cancer cells to regulate their metastatic abilities remain unclear." (PMID 35565279, 2022). "Previous studies have shown that CCL15 can recruit CCR1+ bone marrow-derived inhibitory cells and CCR1+ neutrophils to promote liver metastasis of colorectal cancers 37-39." (PMID 35673582, 2022). "Similarly, in colorectal cancer, THRC1-induced upregulation of CCL15 facilitates the recruitment of CCR1+ macrophages, thereby enhancing tumor progression." (PMID 40740234, 2025). "CCL15 has been suggested to mediate MC infiltration in colorectal cancer, but we were not able to test this cytokine." (PMID 32722549, 2020). "Interestingly, analysis of 333 clinical specimens of primary colorectal cancer showed that CCL15 was expressed mainly at the invasion front, rather than the center of the tumor." (PMID 34458892, 2020).
hepatocellular carcinoma (11 papers, 2019 to 2025). A malignant tumor that arises from hepatocytes. "For instance, in hepatocellular carcinoma, CCL15 recruits CCR1+ monocytes to support immune evasion and metastasis." (PMID 40740234, 2025). "Previous studies have demonstrated that tumor-derived CCL15 promotes the progression of hepatocellular carcinoma by modulating immune cell recruitment and activation, thereby maintaining an immunosuppressive microenvironment." (PMID 40740234, 2025). "The study found that the chemokine CCL15 recruits CCR+ CD14+ monocytes in hepatocellular carcinoma, driving multiple tumor-promoting factors." (PMID 38075694, 2023). "In human hepatocellular carcinoma, most abundantly expressed CCL15 recruited CCR1+ CD14+ monocytes toward HCC invasive margin to enhance tumor metastasis by inducing immune suppression and angiogenesis." (PMID 35267547, 2022). "In contrast, CCL15 was significantly associated with the expression of Hepatitis B virus X protein and negatively correlated with clinical outcome for HBV-positive hepatocellular carcinoma (HCC) patients." (PMID 36235456, 2022). "CCR1, the main and specific receptor for CCL15, is a G protein-coupledreceptor that is expressed by a variety of cells such as monocytes, lymphocytes, neutrophils, eosinophils and hepatocellular carcinoma cells." (PMID 30979374, 2019). "CCL15 is a serum biomarker and independent predictor of survival in hepatocellular carcinoma." (PMID 33182504, 2020). "CCL15 has been postulated as a specific proteomic biomarker of HCC due to its increase in patients’ serum with hepatocellular carcinomas." (PMID 37185750, 2023). "Previous studies mainly reported that CCL15 was involved in the occurrence and development of hepatocellular carcinoma (HCC)." (PMID 35642002, 2022). "Expression of CCL15/HCC-2 is not changed by chronic hypoxia as confirmed by the experiments on lung adenocarcinoma cells and breast cancer cells, although chronic hypoxia may reduce CCL15/HCC-2 expression on the hepatocellular carcinoma cells and primary human monocytes." (PMID 32781743, 2020).
colon cancer (6 papers, 2015 to 2024). "While these reports indicated the role of CCL15 in colon cancer-caused metastasis, our previous work also demonstrated that CCL15 elevated PDAC cell migration and invasion in human-cultured PDAC cell lines that possess the KrasG12D mutation." (PMID 38731942, 2024). "Other groups also reported that in addition to myeloid cells, these colon cancer cells were also able to recruit CCR1+ tumor-associated neutrophils to facilitate lung metastasis through the expression of CCL15." (PMID 38731942, 2024). "Loss of SMAD4 promotes CCL15 expression in colon cancer cells and enables primary tumor invasion and liver metastasis of CRC." (PMID 33799486, 2021). "CCL15 level was associated with liver metastases in patients with colon cancer." (PMID 26875556, 2016). "Human colon cancer cells produced CCL15 to recruit immature myeloid cells (iMCs) from bone marrow and then promoted tumor invasion in the invasion front." (PMID 26875556, 2016). "CCL9 (and CCL15) secreted by mouse and human colon cancer cells has been shown to recruit immature myeloid cells (iMCs), which produce matrix metalloproteinases MMP2 and MMP9 required for successful colonization of the liver." (PMID 25882816, 2015). "The interaction between mast cells and human colon cancer cells is mediated by CCL15 or SCF." (PMID 31799196, 2019). "Similarly, in colon cancer, cancers that lack SMAD4 expressed more CCL15, which attracted CCR1+ myeloid cells, leading to enhanced liver metastasis." (PMID 38731942, 2024).
asthma (5 papers, 2012 to 2024). "MIP-1d(CCL15) is secreted by various cells in normal condition and is elevated in autoimmune disorders such as RA and asthma." (PMID 32117217, 2020). "Recently, the serum level of CCL15 was found to be elevated in patients with severe asthma and it was shown to be reduced by omalizumab, a humanized anti-IgE antibody." (PMID 23258953, 2012). "Expression of CCL15 mRNA was elevated in bronchial biopsy specimens from patients with moderate-to-severe asthma, and its level was higher in moderate asthma." (PMID 23258953, 2012). "We review the role of CCL15 in the pathogenesis of asthma and also discuss the influence of IgE-mediated immunomodulation via CCL15 and its receptor CCR1." (PMID 23258953, 2012). "CCL15 was reduced in asthma patients by omalizumab and ASMCs were considered to be the source of CCL15." (PMID 23258953, 2012). "Although other chemokines, such as CCL3L1 and CCL5, have already been examined in detail to assess their role in asthma, little is known about the possible influence of CCL15 on asthma." (PMID 23258953, 2012). "In addition to its involvement in asthma severity, CCL15, a human orthologue of mouse CCL9, has also been reported to mediate the recruitment of suppressive monocytes to liver cancer and subsequently facilitate metastatic abilities of liver cancer cells." (PMID 38731942, 2024). "Cytokine CCL15 has been reported to play a role in asthma through IgE-regulated immunomodulation since high levels of CCL15 detected in the serum samples of patients with severe asthma can be diminished by a humanized anti-IgE antibody." (PMID 35565279, 2022). "These mediators are also important in asthma, but their relation with the CCL15/CCR1 axis remains unknown." (PMID 23258953, 2012). "Thus, CCL15 could be a potential target for asthma therapy, although little is known about its contribution to the pathophysiology of this disease." (PMID 23258953, 2012). "Here, increased C-C chemokine ligand 6 (CCL6) in asthmatic mice and the human orthologs CCL15 and CCL23 that are highly expressed in asthma patients are described, which are mainly derived from eosinophils." (PMID 33640900, 2021). "Therefore, CCL15/CCR1 signaling could be a target for the treatment of asthma." (PMID 23258953, 2012). "Moreover, CCL15 is elevated in patients with advanced (stage III) sarcoidosis, as well as in patients with moderate-to-severe asthma." (PMID 23258953, 2012). "TNF-α and IFN-γ upregulate CCR1 expression by ASMC, so binding of CCL15 to CCR1 might contribute to the severity and pesistence of asthma." (PMID 23258953, 2012). "In addition, airway smooth muscle cells (ASMCs) have been shown to produce CCL15 in vitro, and these cells express CCR1 in asthma patients." (PMID 23258953, 2012). "CCL15 protein production was observed when basophils isolated from the peripheral blood of asthma patients and nonasthmatic control subjects were stimulated with IL-3." (PMID 23258953, 2012). "CCL15 was elevated in the bronchoalveolar lavage fluid (BALF) obtained from patients with stage III sarcoidosis and in peripheral blood from patients with severe persistent asthma, while anti-IgE antibody therapy reduced the CCL15 level of severe asthma patients." (PMID 23258953, 2012). "Although Th17 cells, Th9 cells, and Tregs may be involved in IgE-mediated asthma and seem to have an influence on ASMC, the associations of these Th subsets with the CCL15/CCR1 axis has not been explored in relation to the pathogenesis of asthma." (PMID 23258953, 2012). "Although the chief role of the CCL15/CCR1 axis has been considered to involve promoting the accumulation of inflammatory cells in the airways of asthma patients; CCL15 may also make a contribution to the severity of asthma and to airflow limitation via effects on ASMC." (PMID 23258953, 2012).
gastric cancer (5 papers, 2010 to 2025). A primary or metastatic malignant neoplasm involving the stomach. "CCL5, CCL22, CCL21, CCL2, and CCL15 were correlated with effector memory CD4 T cell in T1/T2 stage gastric cancer, and the number of cells was associated with the expression of IL3, IL17F, IL18, IL22, and IL31." (PMID 33426088, 2020).
lung cancer (5 papers, 2008 to 2025). A malignant neoplasm involving the lung. "Treatment of nonsmall cell lung cancer reduced the plasma level of CCL15 protein, and this was thought to be related to the influence of CCL15 on angiogenesis." (PMID 23258953, 2012). "In contrast, NFKBIA, PSME3, SPARCL1, CCL15, and APOA1 did not return established entries under these filters and at the time of query, indicating that, within IPA, they are not currently categorized as clinical lung cancer biomarkers." (PMID 41465234, 2025).
mild cognitive impairment (5 papers, 2018 to 2025). "Interestingly, in the analysis of progression on cognitive impairment, we found that an increase in CCL15 levels was associated with an increased MMSE score (HR = 7.9, p = 0.045)." (PMID 35610646, 2022). "Two studies reported significantly different concentrations of markers in individuals with MCI: CXCL11, CCL13, and CCL15 were increased, and CXCL16 and IL-16 were decreased in individuals with mild cognitive impairment compared to controls." (PMID 40711681, 2025). "Chemokines CCL1, CCL2, CCL15, CCL27, CXCL9, CXCL10, and CX3CL1 might be most promising to serve as key molecular markers of cognitive impairment, although more cohort studies with larger populations are needed." (PMID 37291639, 2023). "Significant elevations in plasma CCL15 levels in AD have been reported by others; however, the data showed no changes in CCL15 in mild cognitive impairment." (PMID 35069588, 2021).
liver cancer (4 papers, 2021 to 2024). An epithelial or non-epithelial malignant neoplasm that arises from the liver. "The results of MR analysis showed that significant causal association between CCL15 [OR (95%CI), 0.848 (0.730–0.985), p = 0.03] and CCL23 [OR (95%CI), 1.306 (1.020–1.673), p = 0.03] and malignant neoplasm of liver (finn-b-C3_LIVER_INTRAHEPATIC_BILE_DUCTS)." (PMID 38075694, 2023). "Additionally, in human liver cancer cells, both inflammatory factors and epigenetics regulate CCL15 expression." (PMID 33710810, 2021). "To better investigate the potential mechanism of CCL15, we found that CCL15 was the most highly expressed in liver cancer among 21 solid tumors from the TCGA data, indicating that CCL15 may play important roles in the progression of the liver tumor microenvironment (TME)." (PMID 35673582, 2022). "Cochrane’s Q test did not provide evidence of heterogeneity between CCL15 (p = 0.698) and CCL23 (p = 0.978) and liver cancer." (PMID 38075694, 2023).
ovarian carcinoma (4 papers, 2022 to 2025). A malignant neoplasm originating from the surface ovarian epithelium. "CCL15 mainly correlated with phenotype of ovarian cancer, which showed significantly upregulated in mucinous ovarian cancer." (PMID 35769811, 2022). "Thus, we found that the expression of FZD5 and MED1 correlated with the age, and CCL15 correlated with lymphatic invasion in ovarian cancer." (PMID 35769811, 2022). "The study aimed to investigate the potentiality of chemokines, including MCP-1, CCL15, CCL20, and CXCL14, as biomarkers for differential diagnosis between benign tumors and ovarian cancer (OC)." (PMID 36387204, 2022). "What is important, we found that the expression of CCL15 and FZD5 was relatively low expressed in ovarian cancer cell lines, which also showed relative small proportion weight in the signature." (PMID 35769811, 2022). "In this study, we showed that EVs from ovarian cancer cells upregulated genes related to the inflammatory response, including immune cell–attracting cytokines (CCL2, CCL3/L1, CCL15, CCL18, and CCL20), interleukins (IL1B and IL32), and cell–cell adhesion transcripts (VCAM1 and ICAM1)." (PMID 40689422, 2025).
breast carcinoma (3 papers, 2015 to 2022). "Noteworthy, the CM1 list revealed a set of probes for which little literature exists in relation to breast cancer subtypes: CDCA5, CCL15, COL17A1, GLYATL2, ROPN1, LINC00993 and C6orf211." (PMID 26132585, 2015).
COVID-19 (3 papers, 2021 to 2024). A disease caused by infection with severe acute respiratory syndrome coronavirus 2. "CCL15, a chemokine involved in leukocyte trafficking, was identified as predictor for severe COVID-19." (PMID 38575325, 2024). "Moreover, we identified several other inflammation-related proteins that are linked to COVID-19, such as CD209, CD58, CCL15, CCL28, and MNDA." (PMID 38575325, 2024).
adenoma (2 papers, 2016 to 2024). A neoplasm arising from the epithelium. "In the LNM-positive group compared to the control adenoma, there were significant increases in gene expression for CCL15, SSX1, and KRT5 genes, alongside significant decreases in HLA-E, ITPK1, ANXA1, and TXNIP genes across the head, proximal stalk, and distal stalk regions." (PMID 38256174, 2024).
atherosclerosis (2 papers, 2018 to 2023). A disease characterized by the build-up of fatty material and calcium deposition in the arterial wall resulting in partial or complete occlusion of the arterial lumen. "Increased levels of transcript and circulating levels of CCL15 have been associated with atherosclerosis." (PMID 30595762, 2018). "CCL-15 was shown to contribute to plaque destabilization in the progression of subclinical atherosclerosis." (PMID 38138896, 2023).
Follicular thyroid carcinoma (2 papers, 2016 to 2023). "It was found that CCL15 produced by follicular thyroid cancer cells is responsible for the recruitment of TAMs, which could be inhibited by treatment with a CCL15 blocking antibody." (PMID 36173487, 2023).